LGI1 (leucine rich glioma inactivated 1)
Diseases named in the same sentence as LGI1 in open-access papers (continued):
Sharing a sentence is not in itself a finding about the gene and the disease.
encephalitis (continued). "We found that there was a trend that the incidence rate of seizures was higher in LGI1 AE and anti-GABABR encephalitis than in anti-NMDAR encephalitis." (PMID 32431657, 2020). "18F-FDG-PET imaging was more sensitive than MRI in the diagnosis of anti-LGI1 encephalitis, and BG and MTL hypermetabolism are two distinctive targets for LGI1 AE compared to other subtypes of AE." (PMID 32581996, 2020). "We also described a specific metabolic pattern of 18F-FDG-PET among a cohort of subjects with anti-LGI1 encephalitis and further compared functional PET imaging with structural MRI regarding the diagnosis of LGI1 AE." (PMID 32581996, 2020). "Anti-NMDAR encephalitis is the most common type of AE, followed by anti-leucine-rich glioma-inactivated 1 (anti-LGI1) encephalitis and anti-γ-aminobutyric acid B receptor (anti-GABABR) encephalitis." (PMID 31231392, 2019). "The most common type of AE is anti-NMDAR encephalitis, followed by anti–leucine-rich glioma-inactivated 1 (LGI1) encephalitis and anti–gamma aminobutyric acid B receptor (GABABR) encephalitis." (PMID 31736858, 2019). "Thus in anti‐NMDAR encephalitis, autoantibodies induce receptor cross‐linking and internalization, in anti‐LGI1 encephalitis autoantibodies interfere with protein–protein interactions, and in anti‐GABABR encephalitis autoantibodies may block the function of the target antigen." (PMID 31650706, 2019). "Twenty-three patients were diagnosed as anti-LGI1 encephalitis, and four patients were diagnosed as anti-GABABR encephalitis, and the other one was diagnosed as anti-amphiphysin encephalitis." (PMID 31244751, 2019). "LGI1 is one of the potassium channel complex proteins that binds to ADAM22 and ADAM23, and the major disruptions of LGI1 in LGI1-antibody encephalitis involve the hippocampus and the motor cortex." (PMID 30253786, 2018). "A 72-year-old man with anti-LGI1 encephalitis and a 35-year-old woman with anti-GABABR encephalitis presented frequent seizures at onset and underwent an AED withdrawal 3 and 6 months later, respectively." (PMID 30671012, 2018). "To evaluate the AEDs utilization associated with AE, we focused on seizure in a cohort of patients with anti-NMDAR, anti-GABABR, anti-LGI1, and CASPR2 encephalitis." (PMID 30671012, 2018). "Antibodies of the IgG4 subclass have already been described for LGI1 and Caspr2 encephalitis, and DPPX encephalitis." (PMID 30543686, 2018). "The CSF autoimmune antibody panel was entirely negative, including tests for encephalitis-related antibodies such as LGI1, NMDA, AMPA1/2, and others, making active AE in the CSF less likely." (PMID 40718213, 2025). "The data suggest that patients with anti-NMDAR antibodies might benefit from plasma exchange compared to anti-LGI1- and anti-CASPR2 encephalitis." (PMID 40131535, 2025). "In anti-LGI1 or anti-CASPR2 encephalitis, no influence on the primary outcome was observed when IVIG or PE was administered in addition to ivMP, too." (PMID 40131535, 2025). "However, in patients with LGI1 and CASPR2 antibody encephalitis, BCR maturity predominantly is acquired outside the CNS." (PMID 40510352, 2025). "Several studies have shown that IL-6 is elevated in the CSF of patients with anti-NMDAR encephalitis but not in anti-LGI1 encephalitis, often accompanied by increased IL-17A and CXCL13, suggesting a subtype-specific pattern of Th17-driven inflammation." (PMID 41041342, 2025). "Therefore, the clinical picture of our patient was dominated by features of anti-NMDAR encephalitis, as reflected by the results of the higher anti-NMDAR antibodies titers than anti-LGI1 antibodies." (PMID 39820999, 2025). "When the clinical relapse was being suspected, she had no laboratory evidence supporting relapse of encephalitis, such as hyponatremia, MRI abnormalities, LGI1 antibodies in CSF, or neuropil reactivity on IIF-TBA." (PMID 41164023, 2025).
encephalitis (continued). "Monoclonal antibodies (mAbs) derived from peripheral B cells of LGI1-Ab encephalitis patients elicited memory deficits, but no ictal activity after injection into hippocampal area CA3 of mice." (PMID 39984135, 2025). "LGI 1 encephalitis is largely a non-paraneoplastic autoimmune condition, however anti-LGI1 encephalitis of paraneoplastic origin (20%), although rare, has been described especially with small cell lung Ca (SCLC) and thymoma." (PMID 39734683, 2024). "Furthermore, although slight differences exist in symptoms and blood or CSF examination between COVID-19-related encephalitis and both LGI1-antibody and GABAB-antibody encephalitis, it remains challenging to distinguish them based on clinical features." (PMID 38772979, 2024). "In addition, hallucinations and delusions were less common in anti-NMDAR encephalitis and anti-LGI1 encephalitis compared with anti-GABAB encephalitis and anti-GAD65 encephalitis." (PMID 37945763, 2024). "Similar to what has been described in N-methyl-d-aspartate receptor antibody (NMDAR-Ab) encephalitis,16, -, 18 relapses in patients with LGI1-Ab do not encompass the typical full-blown syndrome, but present instead with fewer and milder symptoms." (PMID 38603771, 2024). "This conclusion is more indirectly supported by the low observed frequency of clonal CSF CD4+ T cells, and the histological absence of TLS despite very few LGI1 or CASPR2 antibody encephalitis brain specimens having been studied." (PMID 38319973, 2024). "The risk of developing seizures was reported at up to 90% in patients with anti-leucine-rich glioma-inactivated 1 (anti-LGI1), anti-gamma-aminobutyric acid A or B (GABA A or B) antibody encephalitis and up to 80% in anti-N-methyl-D-aspartate receptor encephalitis (anti-NMDARE)." (PMID 37278857, 2024). "Anti–N-methyl-D-aspartate receptor (NMDAR) encephalitis, anti–leucine-rich glioma-inactivated 1 (LGI1) encephalitis, and anti–γ-aminobutyric acid-B receptor (GABABR) encephalitis are the most prevalent forms, characterized by the presence of antibodies against neuronal cell-surface antigens." (PMID 39421741, 2024). "Similar patterns were observed in the CSF of patients with leucine-rich glioma inactivated 1 (LGI1) encephalitis, but not in N-methyl-D-aspartate receptor (NMDAR) encephalitis, where many mAbs showed few SHM or were even unmutated." (PMID 39142424, 2024). "Most cases of anti-LGI1 encephalitis are non-paraneoplastic, with good prognoses and low recurrence rates; outcomes are worse for patients with hyponatremia, older age, poor initial treatment response, and recurrent disease." (PMID 39421741, 2024). "Despite being frequently mentioned in the literature, relapses in LGI1-Ab encephalitis have not been systematically described." (PMID 38603771, 2024). "Thus, it is difficult to discriminate between LGI1 and GABAB receptor antibody encephalitis based on visual interpretation of PET images." (PMID 37592180, 2023). "The paroxysmal weakness of the unilateral limb reported in our patients has never been seen in anti-LGI1 encephalitis, and this is the only case report documented on record." (PMID 37304289, 2023). "The predominant psychiatric manifestation of anti-LGI1 encephalitis over the course of almost 2 years without brachio-facial seizures or other neurological symptoms apart from cognitive disorder is rare." (PMID 37275973, 2023). "However, the abnormal metabolisms of LGI1 and GABAB receptor antibody encephalitis in the PET images were similar." (PMID 37592180, 2023). "Rituximab (RTX) was administered to 21 patients as second-line immunotherapy, including 14 patients with anti-NMDAR encephalitis (14/48, 29.2%), 4 with anti-LGI1 encephalitis (4/28, 14.3%), 2 with anti-GABABR encephalitis (2/20, 10%), and 1 with anti-CASPR2 encephalitis (1/7, 14.3%)." (PMID 38152405, 2023).
encephalitis (continued). "Thus, early and accurate discrimination between LGI1 and GABAB receptor antibody encephalitis can inform different cancer screenings, thereby facilitating individualized treatment decisions and improving clinical outcomes." (PMID 37592180, 2023). "Based on adult data, response percentages of most prescribed ASMs in patients with anti-LGI1 encephalitis were not satisfactory while carbamazepine appeared more effective than valproate acid or levetiracetam." (PMID 37179544, 2023). "Initiating immunosuppressive therapy during the FBDS stage of anti-LGI1-encephalitis mostly results in a good outcome without residual cognitive dysfunction." (PMID 36672216, 2023). "A “skip connection” could add features extracted from the previous residual block to the next residual block, preserving as many effective features as possible to discriminate between LGI1 and GABAB receptor antibody encephalitis." (PMID 37592180, 2023). "Identification of specific CSF antibodies has been reported in cases of encephalitis following immunotherapy, with onconeural autoantibodies such as anti-Ma2, anti-Hu, anti-GAD, anti-Yo, anti-NMDA, anti-CASPR2, anti-LGI1, anti-GABABr, and anti-AMPAr detected in case series." (PMID 38132400, 2023). "Thus, it was difficult to discriminate between LGI1 and GABAB receptor antibody encephalitis by the visual assessment of PET images." (PMID 37592180, 2023). "Thus, ML is a potential method for discriminating between LGI1 and GABAB receptor antibody encephalitis based on PET images." (PMID 37592180, 2023). "The first-line efficacy rates of anti-NMDAR encephalitis and anti-GABABR encephalitis were relatively low at 70.2% and 70%, respectively, and the first-line efficacy rates of anti-LGI1 encephalitis and anti-CASPR2 encephalitis were 92.3% and 83.3%, respectively." (PMID 38152405, 2023). "Therefore, this study employed axial image slices to construct a 2D ResNet18 model to discriminate between LGI1 and GABAB receptor antibody encephalitis." (PMID 37592180, 2023). "Furthermore, the sensitivity of positron emission tomography (PET) is higher than that of MRI for detecting LGI1 and GABAB receptor antibody encephalitis." (PMID 37592180, 2023). "Positive MRI findings revealed an hyperintensity on T2/FLAIR sequences in the medial temporal lobe, whereas there were no findings suggestive of LGI1 antibody encephalitis on the CT scans." (PMID 37064193, 2023). "Parietal lobes were more affected by anti-NMDAR than by anti-LGI1 (p = 0.036), resembling ischaemic changes caused by anti-NMDAR (No. 1, No. 2) encephalitis." (PMID 37986052, 2023). "Studies have reported that the pro-inflammatory cytokine IL-6 is elevated in the CSF of patients with anti-NMDAR encephalitis, but this increase is not remarkable in patients with anti-LGI1 encephalitis." (PMID 35937071, 2022). "(We enrolled 35 patients with anti-LGI1 encephalitis and 22 patients with non-inflammatory neurological disease)." (PMID 36685530, 2022). "Surprisingly, anti-LGI1 encephalitis patients typically showed substantial recovery, with none having a moderate or severe deficit at discharge." (PMID 35720290, 2022). "The CASE scale was validated, and the results showed that the CASE score was positively correlated with the mRS score in total AE (r = 0.849, P < 0.001), NMDAR encephalitis (r = 0.868, P < 0.001), LGI1 encephalitis (r = 0.741, P < 0.001) and GABABR encephalitis (r = 0.778, P < 0.001)." (PMID 35844590, 2022). "To date, large cohort studies on the relapse rate and predictors of relapse in anti-NMDAR, anti-GABABR and anti-LGI1 encephalitis are lacking in Northeast China." (PMID 35757705, 2022). "Thirty-five patients with anti-LGI1 encephalitis and 22 patients with non-inflammatory neurological disease were enrolled in this study." (PMID 36685530, 2022).
encephalitis (continued). "However, the sex disparity in the rest of the subtypes was not in concordance with the results of prior studies, which reported male predominance in LGI1, GABAbR, and CASPR2 encephalitis." (PMID 35720290, 2022). "In a retrospective German cohort, 26 out of 61 (43%) patients with anti-LGI1, 11 out of 25 (44%) with anti-CASPR2, 31 out of 84 (37%) with anti-glutamic acid decarboxylase 65 (GAD65), and 81 out of 142 (57%) with anti-NMDAR encephalitis were treated with rituximab." (PMID 35060089, 2022). "Several studies have reported that when using CSF, a negative result was found in 37%-47% of patients with anti-LGI1 encephalitis." (PMID 36591253, 2022). "Nevertheless, for a proportion of patients with anti-LGI1 encephalitis, the metabolic disorders were not yet perceptible." (PMID 35711267, 2022). "However, no large-sample clinical observation and follow-up studies have been conducted to explore the frequency of cerebellar ataxia in patients with anti-AMPAR, anti-LGI1, or anti-GABABR encephalitis by far." (PMID 35250990, 2022). "Patients with anti-NMDAR encephalitis and other rarer subtypes like anti-GABABR, anti-AMPAR, and anti-DPPX encephalitis, can show OCB positive in CSF and /or serum, but patients with anti-LGI1, anti-IgLON5, anti-CASPR2, and anti-GlyR antibodies are rarely OCB positive." (PMID 35937071, 2022). "The patterns of PET signal changes resulting from metabolic abnormalities related to anti-LGI1 encephalitis were similar for CD patients and non-CD patients." (PMID 35711267, 2022). "The general mortality rate of anti-NMDAR, anti-LGI1, and anti-GABABR encephalitis was 15%." (PMID 35320933, 2022). "Most patients presenting with only FBDS at admission did not suffer from serious anti-LGI1 encephalitis." (PMID 36685530, 2022). "The patients with anti-LGI1 encephalitis who were non-completely detectable by visual assessment (non-CD patients)." (PMID 35711267, 2022). "As of 2007, encephalitis owing to anti-N-methyl-D-aspartate receptor (anti-NMDAR) was the most frequent AE subtype, followed by the subtypes due to anti-leucine-rich glioma-inactivated 1 (anti-LGI1) and anti-gamma aminobutyric acid B-receptor (anti-GABABR) antibody." (PMID 35222399, 2022). "We found that in addition to anti-NMDA encephalitis, low-T3 syndrome was also present in anti-LGI1 encephalitis, anti-GABAR encephalitis, and other rare subtypes of encephalitis, suggesting that low-T3 syndrome may be prevalent in multiple subtypes of AE." (PMID 35222399, 2022). "Few patients have anti-CASPR2 encephalitis, anti-GABABR encephalitis, or anti-LGI1 encephalitis." (PMID 35874583, 2022). "For example, 13% of patients with anti‐LGI1 encephalitis did not meet the criteria, nor did 15% of a cohort of mixed autoimmune encephalitides, because those clinical and paraclinical criteria were not sensitive enough." (PMID 33816660, 2021). "A systematic review of LGI1 and CASPR2-related diseases in children showed that 57.1% of CASPR2 positive patients presented with isolated epilepsy, epileptic encephalopathy or seizure disorder, and only 14.3% (2/14) presented with simple encephalitis." (PMID 34660491, 2021). "Over 90% of LGI1-antibody-positive encephalitis patients, of both East Asian and Caucasian extraction, have the HLA-DRB1*07:01allele, while patients with CASPR2-antibody encephalitis have a marked overrepresentation of HLA DRB1*11:0l." (PMID 31655889, 2021). "Except for faciobrachial dystonic seizures (FBDS) in anti-LGI1 AB encephalitis, no specific semiological features are known to be pathognomonic for AE, even in cases of status epilepticus." (PMID 33897594, 2021). "Although this study was not specific to anti-LGI1 encephalitis and the quality of the enrolled literature was heterogeneous, it still reminds us that we should cautiously interpret the intergroup differences here." (PMID 34168612, 2021).
encephalitis (continued). "Thus, it can be concluded that older patients with anti-LGI1 AB encephalitis less frequently have OCB in CSF, whereas, patients with anti-CASPR2 AB encephalitis more frequently show higher cell counts (29%−36%) as well as OCB (23%−32%) in CSF." (PMID 33897594, 2021). "However, not just IgLON5 antibodies are known to result in neuroaxonal degeneration, as shown in a study of patients characterized by LGI1, CASPR2 or NMDAR antibodies and encephalitis." (PMID 34393763, 2021). "NMDAR encephalitis patients (n = 19) were in more severe condition at the onset of the disease with significantly higher mRS score at the time of diagnosis (median: 5, range: 2-5) compared to LGI1, GABABR and Caspr2 encephalitis (n = 11; mRS score at the diagnosis median: 3, range: 2–5) (p = 0.028)." (PMID 33767656, 2021). "Despite prominent clinical features of anti-LGI1 limbic encephalitis (LGI1-LE), the patient also exhibited overlapping symptoms of anti-NMDAR encephalitis, like early-onset GTCS, which might be related to the concomitant positive NMDAR antibodies." (PMID 32894089, 2020). "Encephalitis mediated by antibodies against the N-methyl-d-aspartate (NMDA) receptor is the most frequent subtype followed by encephalitis with antibodies to the synaptic linker protein leucine-rich, glioma inactivated 1 (LGI1)." (PMID 32641101, 2020). "In a study of three patients with anti-LGI1 encephalitis the presence of faciobrachial dystonic seizures was not specified, despite the description of nonspecific seizures in 100% of cases, possibly due to difficulty in distinguishing these two findings." (PMID 33551968, 2020). "Autoimmune encephalitis accounts for 10–20% of cases of encephalitis, with anti-NMDAR encephalitis being the most common, accounting for about 80% of AE patients, followed by anti-LGI1 encephalitis and anti-γ-aminobutyric acid type B receptor (GABABR) Ab-related encephalitis." (PMID 33162923, 2020). "There are more and more reports of patients with anti-LGI1 encephalitis; however, the characteristics of cognitive impairment in patients among the Chinese population with anti-LGI1 encephalitis have not been described." (PMID 33162923, 2020). "Unlike other types of LE, anti-LGI1 encephalitis is infrequently accompanied by tumors, and typically responds well to immunotherapy." (PMID 33510707, 2020). "From May 2013 to April 2019, a total of 18 cases of NSAb-associated AEs were diagnosed in our hospital, including 9 cases of LGI1 AE, 7 cases of anti-NMDAR encephalitis, and 2 cases of anti-GABABR encephalitis." (PMID 32431657, 2020). "The clinical and PSG characteristics in LGI1-Ab encephalitis with status dissociatus (SD) and without SD." (PMID 32849186, 2020). "These clusters showed intensive mutational activity of CSF B cells, providing strong evidence for an independent CNS-based antigen-driven response in patients with LGI1 antibody encephalitis but not in controls." (PMID 32029531, 2020). "Clinical characteristics of AE patients and comparison of the clinical characteristics between the groups with and without coexisting ADs in anti-NMDAR and anti-LGI1 encephalitis patients." (PMID 31736858, 2019). "Our study found two cases with anti-LGI1 encephalitis and one case with anti-CASPR2 encephalitis." (PMID 31507515, 2019). "The coexistence of anti-LGI1 and anti-CASPR2 encephalitis may contribute to seizure, cognitive disturbance, movement disorders, and pain." (PMID 30671012, 2018). "Indeed, this chronic cognitive impairment is a very common sequela of LGI1 and CASPR2 antibody encephalitis and should be a focus of future research." (PMID 29055902, 2018). "LE was the most common syndrome in patients with LGI1 and CASPR2 encephalitis." (PMID 30524441, 2018). "Unlike other limbic encephalitides, LGI1 antibody encephalitis is rarely accompanied by tumors and shows a good response to immunotherapy." (PMID 29980179, 2018).